CDKN2A (cyclin dependent kinase inhibitor 2A)
Diseases named in the same sentence as CDKN2A in open-access papers (continued):
Sharing a sentence is not in itself a finding about the gene and the disease.
meningioma (continued). "In particular, homozygous deletions (homodel) of the cyclin-dependent kinase inhibitor 2A/B (CDKN2A/B) genes on chromosome 9p21 have been associated with significantly shorter time to progression and is now a diagnostic criterion for World Health Organization (WHO) grade 3 meningiomas." (PMID 37093270, 2023). "Finally, even in the absence of a high mitotic index or brain infiltration, atypical meningiomas may feature CDKN2A/B homozygous deletion." (PMID 33670055, 2021). "In meningiomas, genome-wide CNV profiling from off-target reads identified WHO-relevant alterations, including CDKN2A/B deletions and 1p/22q co-deletions, supporting molecular upgrading in 9/58 (16%) of histologically lower grade tumours." (PMID 41834733, 2026). "CDKN2A expression, a RBP biomarker for aggressive meningiomas, is regulated by genetic aberrations and miRNAs in meningiomas and pilocytic astrocytomas 76,77." (PMID 40303323, 2025). "Our results with p16 expression in meningiomas show limited correlation with CDKN2A status, suggesting that MTAP immunostaining is superior to p16 for the evaluation of CDKN2A/B deletion in meningiomas." (PMID 39409918, 2024). "Our analysis thus indirectly confirms that homozygous and heterozygous CDKN2A/B deletions as determined in the included studies is sufficiently robust, to allow for the identification of an independent predictor of PFS in meningioma." (PMID 38017560, 2023). "Additionally, our findings suggest that elevated CDKN2A mRNA expression in meningiomas may serve as a biomarker of clinical aggressiveness in the majority of meningiomas that do not have any CDKN2A deletions (homodel or heterodel), presenting interesting diagnostic and therapeutic implications." (PMID 37093270, 2023). "MTAP immunohistochemistry has been demonstrated to be a surrogate marker for homozygous CDKN2A/B deletions and might highlight patients potentially benefiting from novel therapies inhibiting the promotion of DNA damages and mitotic dysfunction in meningioma cells." (PMID 38017560, 2023). "As both CDKN2A and CDK4 expression were elevated in CDKN2Ahigh meningiomas, we correlated these changes with DNA methylation at their respective loci." (PMID 37093270, 2023). "Although CDKN2A normally negatively regulates CDK4, there was significantly higher CDK4 mRNA expression in CDKN2Ahigh meningiomas compared to CDKN2Alow cases across all cohorts." (PMID 37093270, 2023). "CDKN2A/B homozygous deletions on chromosome 9p21 have been demonstrated to be predictive regarding progression-free survival in WHO grade 2 and 3 meningiomas." (PMID 37370707, 2023). "RNAseq of primary (mng_50, mng_20, mng_84, mng_46) and established meningioma cell lines (IOMM-Lee, CH157) demonstrated increased CDKN2A expression in mng_46 and mng_84 cell lines and decreased RB1 expression." (PMID 37093270, 2023). "When we grouped meningiomas by WHO grade, we found a similar trend of increasing CDKN2A mRNA expression with higher WHO grade." (PMID 37093270, 2023). "There was a significantly higher degree of CpG methylation at the CDKN2A gene, particularly at the gene body and 3’ untranslated region (UTR) of CDKN2Ahigh meningiomas compared to CDKN2Alow tumors across all cohorts." (PMID 37093270, 2023). "No significant heterogeneity was found among the investigations reporting the distribution of CDKN2A/B status in WHO grade 1, 2, and 3 meningiomas." (PMID 38017560, 2023). "This year, molecular alterations, including CDKN2A/B and TERTp, were added to the WHO classification for meningiomas." (PMID 35299730, 2022). "Of note, other common pathological relevant genes of meningiomas, including AKT1 (n = 3; 8%), CDKN2A (n = 2; 5%), SMO (n = 0; 0%), SUFU (n = 0; 0%), POLR2A (n = 6; 16%), TRAF7 (n = 1; 3%), and SMARCB1 (n = 2; 5%), were detected as well." (PMID 34778063, 2021).
meningioma (continued). "Moreover, a next-generation sequencing analysis of 17 recurrent and 13 non-recurrent meningiomas identified three CDKN2A alteration (p.Ala148Thr) mutation, whole homozygous or heterozygous gene loss, or promotor methylation (>8) strongly correlated with recurrence and a Ki67 labeling index > 7%." (PMID 34679551, 2021). "Additional common pathological relevant genes of meningiomas, including AKT1 (n = 3; 8%), CDKN2A (n = 2; 5%), SMO (n = 0; 0%), SUFU (n = 0; 0%), POLR2A (n = 6; 16%), TRAF7 (n = 1; 3%), and SMARCB1 (n = 2; 5%), were observed as well." (PMID 34778063, 2021). "We also observed an enrichment in alterations in CDKN2A/B, KDM6A, ARID1A, PTEN, FBXW7, and SUFU in comparison with NF2-wt meningiomas." (PMID 33087175, 2020). "Interestingly, none of the WHO grade II or III meningioma variants diagnosed according to the proliferation-independent histological patterns, including chordoid, clear cell and rhabdoid meningiomas, showed a homozygous deletion of CDKN2A/B (online resource)." (PMID 32642869, 2020). "Other genetic mutations have also been reported, including phosphatase and tensin homolog (PTEN), cyclin-dependent kinase inhibitor 2A (CDKN2A), and cyclin-dependent kinase inhibitor 2B (CDKN2B) genes which can be found in grade III meningiomas." (PMID 33014773, 2020). "CDKN2A, ARID1A, BRCA1, NF1, and AKT1 were also commonly identified in meningioma samples across the cohort." (PMID 31191822, 2019). "The aim of this study was to evaluate the methylation status of 12 cancer-related genes, namely ERCC1, hMLH1, ATM, CDKN2B (p15INK4B), p14ARF, CDKN2A (p16INK4A), RASSF1A, RUNX3, GATA6, NDRG2, PTEN, and RARβ, in 44 meningioma samples of WHO grade I and II." (PMID 25648363, 2015). "Meningiomas harboring homozygous deletions of CDKN2A/B are characterized by high recurrence rates independent of WHO grade, DNA methylation class, sex, age, and tumor location." (PMID 39358739, 2024). "CDKN2A/B HoDe was absent in 238 grade 1 cases, present in only 7/213 (3.2%) grade 2 meningiomas, and found in only 30/1358 (2.2%) grade 1 and 2 cases in another series." (PMID 37296907, 2023). "Although CDKN2A HeDe is not currently considered as a criterion for upgrading meningiomas to CNS WHO grade 3, it was recently suggested to predict shorter RFS in patients with meningiomas." (PMID 37014425, 2023). "There were no CDKN2Ahigh meningiomas with copy number gain of 9p at the chromosomal arm level or at the CDKN2A gene level." (PMID 37093270, 2023). "In addition, hypermethylation of TIMP3, Cyclin-Dependent Kinase Inhibitor 2A (CDKN2A), and TP73 has been correlated with meningioma grade." (PMID 38001599, 2023). "CDKN2A deleted meningiomas did not harbour SMARCB1, AKT1, PIK3CA, SMO, POLR2A, or RB1 somatic mutations." (PMID 37093270, 2023). "CDKN2A expression appeared to increase in a stepwise manner with more aggressive MG, showing the highest levels in MG3 (hypermetabolic) and MG4 (proliferative) meningiomas." (PMID 37093270, 2023). "Despite there are very strong data supporting the prognostic importance of homozygous CDKN2A/B deletions in terms of meningioma progression, the impact of heterozygous CDKN2A/B deletions on progression-free survival (PFS) is not entirely clear so far." (PMID 38017560, 2023). "Our findings, obtained in a cohort of only primary atypical meningiomas that underwent total resection, further support the negative prognostic significance of CDKN2A HeDe in meningiomas." (PMID 37014425, 2023). "This is particularly pertinent given that CDKN2A deleted meningiomas did not have significantly worse outcomes compared to other MG4 meningiomas without this alteration." (PMID 37093270, 2023). "With the recent 2021 update of the WHO Classification of Central Nervous System Tumours, homozygous deletions of CDKN2A/B are sufficient to designate meningiomas as CNS WHO grade 3 tumors regardless of histological grading." (PMID 36181606, 2023).
meningioma (continued). "Three meningiomas (cases #5, #6, and #7, all morphologically grade 2) with no identifiable CDKN2A alteration had absence of p16 immunoreactivity." (PMID 36723772, 2023). "In our meta-analysis of IPD from 2521 meningioma patients, both heterozygous and homozygous CDKN2A/B deletions are a negative prognostic factor regarding the probability of PFS." (PMID 38017560, 2023). "The 2021 update additionally reports commonly altered genes in meningiomas, but largely does not use them as grading criteria with the exception of CDKN2A/B homozygous deletion and TERT promoter mutation as diagnostic for grade 3 meningiomas." (PMID 36033542, 2022). "Interestingly, most cases with sequence alterations in BAP1, CDKN2A/B, and TERT occurred in meningiomas with a low-grade cytogenetic background." (PMID 35299730, 2022). "Our findings show that CDKN2A/B homozygous deletion can be also found in atypical meningiomas, in the absence of a high mitotic index." (PMID 33670055, 2021). "One study that compared the gene coding sequences of recurrent and non-recurrent meningioma found that changes in the CDKN2A gene were only observed in recurrent meningioma." (PMID 33042832, 2020). "In our study, fibroblastic meningioma was detected with increasing expression of CCND1, CDK6, and E2F3, and decreasing expression of CDKs inhibitors including CDKN1A, CDKN2A, and CDKN2B, suggesting a role of cell cycle deregulation in the tumorigenesis of fibroblastic meningioma." (PMID 23285163, 2012). "It has been reported that the majority of anaplastic meningiomas either show homozygous deletions of CDKN2A, p14ARF, and CDKN2B, mutations in CDKN2A and p14ARF, or lack of expression of one or more of these genes." (PMID 23285163, 2012). "Genetic alterations of the Nf2 gene are present in 60% of sporadic meningiomas regardless of grade, suggesting their initiating role in meningeal tumorigenesis; meanwhile, CDKN2A (p16INK4a), p14ARF, and CDKN2B (p15INK4b) are thought to be responsible for progression to higher grades of meningioma." (PMID 39996452, 2025). "Although MTAP staining offers the benefit of labeling normal cells as an internal (positive) control, our work shows that it is not always a dependable surrogate marker for CDKN2A status, particularly in anaplastic meningiomas with differing CDKN2A and MTAP statuses." (PMID 40227557, 2025). "p16 immunohistochemistry could not reliably differentiate between meningiomas with and without CDKN2A deletions but appeared to correlate better with mRNA expression." (PMID 37093270, 2023). "Among tumors with intact CDKN2A/B (without a homozygous or heterozygous deletion), we found a distinct difference in outcome based on mRNA expression of CDKN2A, with meningiomas that had elevated mRNA expression (CDKN2Ahigh) having a significantly shorter time to recurrence." (PMID 37093270, 2023). "For instance, it might be possible that in a subtotally resected meningioma the analyzed tumor tissue does not necessarily contain the hotspot region with the maximum aggressive behavior showing CDKN2A/B deletions." (PMID 38017560, 2023). "Therefore, anaplastic meningiomas are now diagnosed if TERT promoter mutations and/or CDKN2A/B homozygous deletion occur, even in the absence of histological features consistent with anaplasia." (PMID 36661712, 2023). "In our study, even though institution 1 showed high sensitivity and specificity for p16, given the inconsistency between the institutions and the high amount of faint positive staining, p16 alone might not be as good as MTAP for determining CDKN2A/B status in meningiomas." (PMID 39409918, 2024). "However, meningiomas of the malignant class (Molecular Group 4) show the most biologically aggressive behavior and CDKN2A/B might not provide additional prognostic information in this group." (PMID 38017560, 2023).
meningioma (continued). "Among a series of 17 recurrent and 13 non-recurrent meningiomas, CDKN2A/B alterations were found only in recurrent meningiomas, and a novel SNV (p.Ala148Thr) was identified in 5 recurrent meningiomas, further supporting the association between CDKN2A/B alterations and meningioma recurrence." (PMID 36686824, 2022). "Therefore, studies encompassing a larger series still need to evaluate whether or not CDKN2A alterations can be used as biomarkers of recurrence in meningioma." (PMID 33014773, 2020). "As our study commenced prior to the publication of WHO CNS 5, meningioma grading was based solely on histopathology without integrated molecular profiling (H3K27me3, TERT promoter, CDKN2A/B status undetermined)." (PMID 41358608, 2025). "CDKN2A HeDe was present in 14 meningiomas ICH-G3, in one meningioma IHC-G2 and absent in all meningiomas IHC-G1 (P = 0.0462)." (PMID 37014425, 2023). "Although TERT promoter mutations and CDKN2A/B deletions are known to confer WHO grade III meningiomas in the latest WHO grades for CNS tumours, we did not evaluate the respective molecular analyses (TERT promoter and CDKN2A/B deletion) and utilised the 2016 WHO classifications." (PMID 37752594, 2023). "However, unlike at the transcriptomic level, where meningiomas with CDKN2A homodel had the highest CDK4 expression, CDKN2A homodel meningiomas showed lower levels of CDK4 protein, although only 3 tumors in this group were profiled here." (PMID 37093270, 2023).
mesothelioma (109 papers, 2009 to 2026). A usually malignant and aggressive neoplasm of the mesothelium which is often associated with exposure to asbestos. "Overall, our data question the widespread assumption of MTAP as a universal surrogate for CDKN2A status across all mesothelioma subtypes, underlining the need for site‐specific validation." (PMID 40566743, 2025). "In asbestos-induced mesotheliomas, CDKN2A mutations often occur after biallelic inactivation of NF2, another key tumor suppressor gene." (PMID 40362535, 2025). "Approximately 10% of mesothelioma patients harbor germline mutations in cancer susceptibility genes, predominantly involving CDKN2A, neurofibromatosis type 2 (NF2), and BRCA1‐associated protein 1 (BAP1)." (PMID 40904706, 2025). "CDKN2A loss was positively correlated with the aggressiveness of clinical behavior in mesotheliomas." (PMID 37626750, 2023). "While NSCLC is characterised by activating mutations in oncogenes, mesothelioma on the other hand is characterised by the frequent inactivating alteration of the CDKN2A, NF2 and BAP1 tumour-suppressor genes." (PMID 38015374, 2023). "Preclinical models of mesothelioma confirm that specific alterations can lead to different outcomes, for example, CDKN2A loss leads to poor outcomes and BAP1 alterations in combination with NF2 and CDKN2A/B to rapid disease onset." (PMID 36138075, 2022). "To date, there are no studies demonstrating the correlation between SETDB1 and the three most frequent mutated genes (BAP1, NF2, and CDKN2A) in mesothelioma." (PMID 34299035, 2021). "The first and most common mutation described in mesothelioma is the deletion of the Cyclin D dependent Kinase inhibitor 2A (CDKN2A) gene on chromosome 9, accounting for approximately 70% of MPM cases." (PMID 34830817, 2021). "Of particular importance is the epigenetic silencing of the CDKN2A locus, a well-known driver mutation in asbestos-induced mesothelioma, observed in mice exposed to both long MWCNTs and long amosite fibers." (PMID 33804168, 2021). "The most common genetic alterations associated with mesothelioma, including CDKN2A deletions and NF2 mutations, have been known for about two decades." (PMID 25952750, 2015). "We would like to add here for the biological significance of our results that homozygous deletion of CDKN2A/2B is frequently observed in human mesothelioma associated with asbestos exposure." (PMID 22952676, 2012). "Additionally, mesothelioma is characterized by the frequent loss or mutation of tumor suppressor genes such as cyclin dependent kinase inhibitor 2 A (CDKN2A), BRCA1 associated protein 1 (BAP1), neurofibromin 2 (NF2), and cullin 1 (CUL1)." (PMID 40223054, 2025). "BAP1 and CDKN2A are the most common inactivating mutations in mesothelioma." (PMID 37880686, 2023).